BCLAF1 (BCL2 associated transcription factor 1)
Diseases named in the same sentence as BCLAF1 in open-access papers (continued):
Sharing a sentence is not in itself a finding about the gene and the disease.
cancer (continued). "In the TCGA cancer genomics dataset, the transcription factors (TFs) BCOR (BCL6 corepressor, FDR = 1.2 × 10–35) and BCLAF1 (Bcl-2-associated transcription factor 1; ActiveDriver FDR = 9.8 × 10–4) were significantly enriched in substitutions in glycosylation sites." (PMID 33834021, 2021). "CSMD3 and BCLAF1 are among the general cancer genes and SCLC-related genes." (PMID 29050228, 2017). "These included genes involved in cell death and survival processes (BCLAF1, CFLAR, CASP1, and XIAP), genes associated with proliferation-driving transcription or cancer (KLF4, LEF1, SOX4, ID3), and genes associated with inflammation (CD28, CCR7, CX3CR1 and IFNG)." (PMID 28407008, 2017). "Given the role of THRAP3/BCLAF1 in the regulation of DDR proteins, we hypothesized that some cancer-associated mutations within THRAP3, particularly those that result in loss of THRAP3 structure/function, may confer a DNA repair defect on cells harboring these mutations." (PMID 29112714, 2017). "Bclaf1 binds to SPOP, thereby inhibiting PD-L1 ubiquitination and degradation and making cancer cells sensitive to checkpoint therapy, suggesting that Bclaf1 is a novel therapeutic target for enhancing anti-tumor immunity in HCC." (PMID 39444606, 2024). "These indicated the significance of Ser290 phosphorylation in the involvement of BCLAF1 in DDR and subsequent cancer cell apoptosis." (PMID 34372878, 2021). "Other genes, such as SH2D4A, BCLAF1, and SUV420H, also have carcinogenic or tumor-suppressing functions that can affect the formation and development of human cancer." (PMID 32079071, 2020). "By investigating the target genes of NRSF and BCLAF1 from our constructed GRN, we want to see which pathways these two regulators are involved in and how they are related to cancer." (PMID 25539927, 2015). "Thus, BCLAF1 enhances PD-L1 stability and expression through SPOP functional inactivation, resulting in cancer cells evading immune surveillance." (PMID 38340178, 2024). "Larger pan-cancer cohorts will allow us to test the assertion that BCLAF1 helps identify TMB-high ICB non-responders." (PMID 35803911, 2022). "Using knockdown approaches of GTF2-I or BCLAF-1 we showed that these two transcription factor do not participate to the regulation of cancer cells migration." (PMID 31527668, 2020). "Moreover, as cancer associated mutations within THRAP3 result in deregulated export of target transcripts and a subsequent DNA repair defect, this data suggests that THRAP3/BCLAF1 may function to suppress tumor development and/or act as biomarkers of response to therapy." (PMID 29112714, 2017).
tumor (34 papers, 2016 to 2026). "Particularly, the phosphorylation of Bcl-2-associated transcription factor 1 (BCLAF1) at Ser290 was significantly upregulated in tumor." (PMID 34372878, 2021). "The diverse function of Bclaf1 can be partially explained by itself being a subject of splicing regulation, with one specific splicing isoform implicated in regulation of tumour growth (Zhouet al., 2014)." (PMID 35865489, 2021). "In the entire cohort of primary tumours, we disclosed three variants—deletions in BCLAF1 and OVCH2 and substitution in OR2T35—and 26 mutated genes that were mutated in >30% of all cases, being part of a global mutational signature of HPV+ TSCC/BOTSCC." (PMID 35008243, 2021). "Therefore, we hypothesized that Bclaf1 is able to induce VEGFA expression to promote tumor-associated angiogenesis and consequently tumor growth." (PMID 30367150, 2019). "One tumor had only a point mutation in NTRK1, while the remaining tumor showed 11 heterozygous deletions, including in ROS1, BCLAF1, and ARID1B, which were frequently altered in the entire cohort." (PMID 40227833, 2025). "To determine the regulatory mechanism governing BCLAF1 expression in patients receiving immunotherapy, we next sought to explore the hypoxic tumor microenvironment, which interacts with the immune microenvironment." (PMID 37906282, 2023). "The most common variants were deletions in BCLAF1 and OVCH2, both present in 12 samples each, followed by a substitution of OR2T35 found in 11 primary tumour samples." (PMID 35008243, 2021). "The IHC results of tumor tissue showed that CK inhibited Bclaf1 expression in a dose-dependent manner in the DEN-rat model." (PMID 33363466, 2020). "Bclaf1 depleted Huh7 cells (with a stably integrated BCLAF1-shRNA expression construct) and control cells were injected subcutaneously into nude mice to establish a xenograft tumor model." (PMID 30367150, 2019). "HIF-1α and Bclaf1 levels were significantly higher in tumor tissues than in adjacent normal tissues, and the levels of Bclaf1 and HIF-1α were positively correlated (r = 0.9004, p < 0.01)." (PMID 30367150, 2019). "Additional confidently classified W-ex mutations from the cell line data that were noted to act in a similar manner as LDHB and have been shown to positively influence tumor progression are BCLAF1, JAK2, and KMT2D49–51." (PMID 31484939, 2019). "Binding of Bclaf1 to H2AX activated the tumor suppressing effects of Bclaf1, thus inducing cell death." (PMID 29795334, 2018). "In tumor cells, BCLAF1, a nuclear protein, can be sequestered into the cytoplasm by the antiapoptotic BCL2 family members, blocking its pro-apoptotic activity." (PMID 29487711, 2018). "The ASE genes that was mostly recurrently observed in both tumor and normal samples had a high allele imbalance, such as AP3P1, BCLAF1, STED8, PRIM2, IL32, SEC22, and MAP2K3." (PMID 30538721, 2018). "However, the mutations in the SBC motif disrupted the ability of BCLAF1-WT to regulate tumor immunity providing BCLAF1 and its SBC motif an attractive target for designing antitumor therapies in HCC." (PMID 38340178, 2024). "In vivo, the overexpression of BCLAF1 accelerated tumor growth and lung metastasis in mice." (PMID 37906282, 2023). "The expression of CTGF and MYB was significantly higher in HCC tissues than that in the adjacent non-tumor tissues (p < 0.05), while the expression of BCLAF1, IFNGR1, and HIVEP2 was significantly lower in HCC tissues than in adjacent non-tumor tissues (p < 0.05)." (PMID 34616668, 2021). "MiR-194-5p acted as the tumor suppressor gene through regulating BCLAF1 expression." (PMID 33188158, 2020). "Knockdown of BCLAF1 blocked phospho-FHL1-mediated tumor growth." (PMID 32587768, 2020).
tumor (continued). "Also, in tumor tissues, depletion of Bclaf1 considerably suppressed the expression of HIF1A, explaining the decrease of VEGFA protein levels." (PMID 30367150, 2019). "Bclaf1 repression significantly reduced the growth of tumor xenografts in nude mice." (PMID 30367150, 2019). "It has been known that Bclaf1 is a H2AX-dependent tumor suppressor." (PMID 29795334, 2018). "Moreover, it was found that tumor cells suppress BCLAF1 expression inducing a cascade of antiapoptotic cellular events that all together determine an increase survival of tumor cells." (PMID 29113313, 2017). "In addition, knockdown of SPOP effectively reversed the effects of BCLAF1 knockdown on apoptosis, cell cycle, and secreted cytokines of Jurkat cells, indicating that BCLAF1 partially depended on SPOP to participate in the suppression of the anti-tumor immune microenvironment." (PMID 38340178, 2024). "However, the function of BCLAF1 in the tumor immune microenvironment is still unclear." (PMID 38340178, 2024). "Since mutants of the SBC-associated BCLAF1 display deficiencies in BCLAF1-SPOP interactions and BCLAF1's regulation of the SPOP-PD-L1 axis, we investigated whether BCLAF1-mSBC influences BCLAF1's function in HCC tumor immunity." (PMID 38340178, 2024). "In conclusion, we found a specific CDC27 variant unique for tumours of HPV+ OPSCC patients with relapse, as well a common mutational signature for HPV+ OPSCC patients independent of the outcome, comprising keratin-associated proteins and mucins, but also specific variants, such as a BCLAF1 variant." (PMID 35008243, 2021). "Furthermore, phosphorylated FHL1-stimulated tumor cell growth appeared dependent on BCLAF1." (PMID 32587768, 2020). "Current evidence supports the role of BCLAF1 as an oncogenic protein in HCC, whereas SPOP has been reported as an tumor suppressor in HCC." (PMID 38340178, 2024). "Only six genes were present in both tumor initiation and tumor evolution stage: MUC4, MUC16, USP6, BCLAF1, KMT2C, and NOTCH2." (PMID 34918496, 2022). "Apart from KRAS and PIK3CA, other genes preferentially altered in the right-sided primary tumor sites, such as PRKDC, ERBB3, BCLAF1 and NOTCH1, have been reported to be correlated with poor prognosis or migration in CRC." (PMID 34281583, 2021). "These in vitro data explain why levels of Bclaf1, HIF-1α, and HIF-1α targets positively correlate with each other in clinical HCC samples, and also correlated with tumor weight in a xenograft HCC tumor model." (PMID 30367150, 2019). "To explore the expression and role of BCLAF1 in the development of HCC, we analyzed the expression of BCLAF1 in HCC and normal liver tissues from The Cancer Genome Atlas (TCGA), Gene Expression Omnibus (GEO), and Clinical Proteomic Tumor Analysis Consortium (CPTAC) databases." (PMID 38340178, 2024). "In this work, we demonstrate that BCLAF1 competitively inhibits SPOP-mediated ubiquitination and degradation of PD-L1 by interacting with SPOP to maintain PD-L1 expression, ultimately promoting immune evasion and tumor progression of HCC." (PMID 38340178, 2024). "The results indicated that the mRNA expression levels of BCLAF1 were positively correlated with PD-L1 (CD274), and consistent findings were obtained using Tumor Immune Estimation Resource (TIMER) database and Gene Expression Profiling Interactive Analysis (GEPIA) database based on TCGA analysis." (PMID 38340178, 2024).
tumor (continued). "Meanwhile, our deepen study suggests that PVT1 acts as a significant tumor regulator and PVT1-miR-194-5p-BCLAF1 axis participates in BC progression, which emerges its possibly clinical application of BC as a meritoriously clinical diagnosis and treatment strategies." (PMID 33188158, 2020). "Thus, we further explored the effect of Bclaf1 on HIF-1α transcription and protein levels and the biological significance of Bclaf1 in HCC angiogenesis and tumor progression under hypoxic conditions." (PMID 30367150, 2019). "In addition, 3 variants and 26 mutated genes, including CDC27, BCLAF1 and AQP7, were present in at least 30% of all primary tumours independent of prognosis." (PMID 35008243, 2021).
infection (8 papers, 2016 to 2025). The state of being infected such as from the introduction of a foreign agent such as serum, vaccine, antigenic substance or organism. "BCL2-associated transcription factor 1 (BCLAF1) is targeted by miR-K12-5 and miR-K12-9; IKKε is repressed by miR-K12-11, leading to lytic infection." (PMID 36851643, 2023). "Knockdown of BCLAF1 led to decreased STAT1 and STAT2 phosphorylation, and increased susceptibility to infection by alphaherpesvirus in lung and brain tissue of mice." (PMID 35803911, 2022). "Western analysis showed that Bclaf1 was silenced effectively in lungs of the mice treated with Bclaf1 siRNAs on 3 days post infection (dpi)." (PMID 30682178, 2019). "Here, we report Bcl-2 associated transcription factor 1 (Bclaf1) is degraded during the alphaherpesvirus Pseudorabies virus (PRV) and Herpes simplex virus type 1 (HSV-1) infections through the viral protein US3." (PMID 30682178, 2019). "Infection of AAV9-Cas9-Bclaf1 partially knocked out the protein expression of Bclaf1." (PMID 33483496, 2021). "Furthermore, they identified two distinct viral mechanisms to antagonize BclAF1: firstly, BclAF1 was shown to undergo proteasomal degradation immediately after infection." (PMID 33530304, 2021). "Since a key feature of herpesviruses is the establishment of a persistent infection and reactivation upon stress, Bclaf1 may participate in these processes." (PMID 30682178, 2019). "Here, we report alphaherpesvirus induces degradation of a host protein, Bclaf1, via its expressed viral protein US3 upon infection." (PMID 30682178, 2019). "Infection occurs in a Poisson distribution and requires tegument-mediated and proteasome-dependent degradation of intrinsic antiviral factors (e.g., Daxx, PML, BclAF1, etc.)(10, –, 12)." (PMID 39655950, 2025). "Recent studies indicate that downregulation of BclAF1 is not specific for HCMV but also occurs during infection with pseudorabies virus and HSV-1." (PMID 33530304, 2021). "Moreover, hematoxylin-and-eosin staining showed greater inflammatory damage in the lungs of Bclaf1-knockdown mice, such as hyperemia, edema, leakage and swelling, relative to those in the lungs of control mice, after PRV ΔUS3 infection for 6 days." (PMID 30682178, 2019). "Consistently, infection of cells expressing a BclAF1 transcript with a 3’UTR lacking the miR-UL112-1 binding site prevented HCMV spread, further suggesting that BclAF1 acts as physiologically relevant RF that needs to be neutralized by virus-specific mechanisms." (PMID 33530304, 2021).
cardiovascular diseases (1 paper, 2025). "We selected top three proteins, Map7 domain-containing protein 1 (Map7D1) 17, Bcl-2-associated transcription factor 1 (Bclaf1) 18,19 and CPT1b 20,21, which were closely related to cardiovascular diseases, for further investigation." (PMID 40093901, 2025).
ischaemic heart disease (1 paper, 2023). "This is the first evidence of the underlying mechanism of BCLAF1 in cardiac I/R injury and may indicate its role as a potential therapeutic target for ischaemic heart disease." (PMID 37215497, 2023).
BCLAF1 also shares sentences with these, for which no sentence is quoted: lung carcinoma (3 papers); diffuse large B-cell lymphoma (2); lung adenocarcinoma (2); melanoma (2); multiple myeloma (2); autoimmune disease (1); cardiac ischemia (1); esophageal squamous cell carcinoma (1); Fanconi Anaemia (1); fibrosarcoma (1); glioblastoma multiforme (1); ischemia (1); ischemic heart disease (1); non-small cell lung carcinoma (1); renal cell carcinoma (1); sleep disorder (1); T-LGL leukemia (1); tubular adenoma (1); villous adenoma (1).